FGFR2 (fibroblast growth factor receptor 2)
Diseases named in the same sentence as FGFR2 in open-access papers (continued):
Sharing a sentence is not in itself a finding about the gene and the disease.
cancer (522 papers, 1992 to 2026). A tumor composed of atypical neoplastic, often pleomorphic cells that invade other tissues. "One gene, FGFR2, showed a well-known cancer-related hotspot mutation p.Lys659Glu and three other mutations." (PMID 40016412, 2025). "FGFR2 dysregulation in cancer can occur via amplification, mutation, or protein overexpression, which have distinct biological and clinical implications." (PMID 40871637, 2025). "Among FGFR family members, FGFR2 plays a critical role in cancer progression through activating mutations, fusions, or amplifications." (PMID 41019981, 2025). "It is necessary to examine the effect of FGFR2 inhibitors for cancer with FGFR2 amplification or FGFR2 mutation." (PMID 41226813, 2025). "Prior studies indicate that acquired resistance to first-generation FGFR inhibitors is mediated, in part, by point mutations in the kinase domain of FGFR2/3 driven cancers." (PMID 38602417, 2024). "In the broader landscape of cancer research, FGFR2 has been implicated in various tumors, with well-documented genetic aberrations such as gene amplifications, mutations, and structural variants." (PMID 38395755, 2024). "A noteworthy finding is that 90% of patients diagnosed with ICC and having KRAS mutations also showed positive findings for FGFR2 fusions, suggesting a potential collaborative role in promoting the progression of malignant tumors." (PMID 38831455, 2024). "This dysregulation is associated with various cancers and developmental disorders, highlighting the importance of FGFR2 in the broader context of RTK-mediated diseases." (PMID 38674107, 2024). "In the cancer genome atlas (TCGA) patient cohort, FGFR2-amplified GCs were most frequently associated with the CIN (8%) and GS (9%) molecular subtypes." (PMID 38791079, 2024). "It is a first-in-class afucosylated monoclonal antibody against the FGFR2b splice variant frequently overexpressed in FGFR2- amplified G/GEJ cancers." (PMID 37245017, 2023). "A study of cancer samples showed a high number of variations and copies in susceptible loci 2q35, 3p24, 17q23, and FGFR2 in patients undergoing treatment." (PMID 38156855, 2023). "Although all the site mutations we identified were situated in the FGFR2 extracellular region, pan-cancer study outcomes reveal that FGFR2 mutation sites are distributed across all exons." (PMID 37964396, 2023). "It provides a specific, high-throughput approach for studying FGFR2-related disorders, enabling more effective personalized treatment strategies for cancers harboring FGFR2 mutations." (PMID 37759450, 2023). "Further, we showed that the FGFR2 Y375C mutation enhances cancer growth and is targetable by the FGFR inhibitor futibatinib." (PMID 37980453, 2023). "Rarely, SB-PCCs showed high microsatellite instability, mutations in IDH1 and ERBB2 genes, or FGFR2 amplification (one case each), which are established or promising therapeutic targets in such aggressive cancers." (PMID 36812376, 2023). "Recently, epithelial splicing regulatory proteins (ESRPs) have been shown to regulate the alternative splicing of FGFR2 to affect EMT-associated cancer cell metastasis in pancreatic cancer, non-small cell carcinoma and colorectal carcinoma." (PMID 37090731, 2023). "To determine the potential effects of fibroblast‐released FGF7 in EC, we investigated the influence of EC patient‐derived cancer‐associated fibroblasts (CAFs67) on the migration of invasive FGFR2‐mutant EC cells." (PMID 37165578, 2023). "Understanding the functional characteristics of FGFR2 mutations holds great significance in identifying potential therapeutic targets and guiding personalized treatment strategies for patients with FGFR2 mutations in various diseases, including cancer." (PMID 37759450, 2023).
cancer (continued). "ESRPs have been shown to regulate the alternative splicing of FGFR2 to affect EMT-associated cancer cell metastasis in some types of cancers." (PMID 37090731, 2023). "By unraveling the distinct effects of different mutations, our study contributes to the identification of personalized treatment strategies for patients with FGFR2-mutated cancers." (PMID 37759450, 2023). "This assay represents a significant advancement in personalized treatment approaches for cancers with FGFR2 mutations, as the existing characterization methods have been limited by their lack of specificity and high-throughput capabilities." (PMID 37759450, 2023). "Although FGFR2 aberrations, including gene amplification, fusion, mutation, and overexpression, have been detected in various types of cancer, clinically available treatment options are limited." (PMID 35342406, 2022). "We propose that cancers containing any FGFR2 variant with a truncated E18 should be considered for FGFR-targeted therapies." (PMID 35948633, 2022). "A better understanding of the determinants defining the oncogenicity and clinical actionability of FGFR2 structural variants is therefore critical for precise matching of cancer patients to FGFR-targeted therapies." (PMID 35948633, 2022). "All four types of FGFR (FGFR1–4) have been associated with specific cancer types, and FGFR2 alteration has been most widely found in GC." (PMID 36292044, 2022). "A t(4:17) translocation at 16.5 embryonic day disrupted Ccnd3; Fgfr2 has tyrosine kinase activity and is frequently mutated in cancer." (PMID 35869059, 2022). "For example, multiple SNPs located in the second intron of FGFR2 cause the increased expression of FGFR2 linked to cancer progression." (PMID 35176995, 2022). "Elevated FGFR2 is associated with an aggressive cancer phenotype and resistance to targeted therapy, making FGFR2-TTCs an attractive therapeutic option." (PMID 36726355, 2022). "Somatic CDH1 mutations and FGFR2 copy number gains both can facilitate cancer progress and result in more aggressive oncology conditions." (PMID 35498538, 2022). "Multiple studies proved the importance of FGFR gene mutations in the development of this cancer, especially FGFR2 fusion with the essential p.V565F gate-keeper mutation." (PMID 36497187, 2022). "MLH1 R659* is a recurrent mutation in various cancers and was deduced to be oncogenic loss-of-function mutation, whereas FGFR2 R6P was deduced to be benign." (PMID 35008475, 2021). "Then, we explored FGFR2 alteration patterns, mutation patterns, and their functional impact and clinical therapeutic implications in distinct cancers and investigated FGFR2 copy number variant (CNV) patterns and their impact on gene expression." (PMID 33968743, 2021). "Enhanced FGFR2 signaling, mediated by FGFR2 alterations containing genetic amplification, mutation, and fusion, has been observed in several cancers and is associated with tumorigenesis." (PMID 33968743, 2021). "A number of studies have reported that cancer-associated RTKs, such as EGFRs, fibroblast growth factor receptor-2 (FGFR2), EphA2, and hepatocyte growth factor receptor (HGFR), all carry truncated O-glycans in their extracellular domains." (PMID 34944925, 2021). "The location distribution of these FGFR2 somatic mutations was quite different among different cancer types." (PMID 33968743, 2021). "Broad-spectrum inhibitors have been successfully utilised in other cancers, such as dual inhibition of PDGFRa and FGFR2 by pazopanib in SMARCB1-deficient rhabdoid tumours." (PMID 34764236, 2021). "The most common cancer types with FGFR2 mutations were CHOL (12.3%), UCEC (10.5%), SKCM (8.8%), and STAD (4.2%)." (PMID 33968743, 2021). "Here, 309 FGFR2 somatic mutations were observed across 32 cancer types and were broadly distributed across different functional domains of FGFR2." (PMID 33968743, 2021).
cancer (continued). "As previously said, BTCs are known to harbor one of the highest frequencies of targetable molecular alterations across cancer types, including FGFR2 fusions or IDH1/2 mutations." (PMID 33805461, 2021). "CIT overexpression has been associated with cancers of various origin, likely through its kinase function that is, however, lost during chromosomal rearrangement in the FGFR2-CIT fusion." (PMID 34207779, 2021). "The genetic alterations of FGFR2 were reported to enhance downstream signaling and are associated with cancer development and progression." (PMID 31894857, 2020). "Fgfr2, a gene for encoding fibroblast growth factor receptor 2 (FGFR2), proved to regulate several growth-related signaling pathways in cancer." (PMID 30906419, 2019). "What effect does cancer treatment have on levels of spontaneous selfish fibroblast growth factor receptor 2 (FGFR2) point mutations in human sperm?" (PMID 31348830, 2019). "The percentages of RAS mutated cases were 50% and 29% among primary cancer with FGFR2 and FGFR1 overexpression, respectively." (PMID 30181810, 2018). "We confirmed known gene interactions of PRPF8 and GRIA1 in testis and brain cortex, and observed a novel interaction of FGFR2, in breast and prostate, modulated by cancer risk-variants." (PMID 30545302, 2018). "Through retrieving the published literature, our study revealed that FGFR2 gene, which had been involved in various cancers, was association with AML risk for the first time." (PMID 27903959, 2017). "It has been previously highlighted that a number of cancer mutations, in particular in FGFR2 and FGFR3, have also been described in various developmental syndromes such as bone dysplasia." (PMID 26992226, 2016). "The cancer risk allele (C) triggers stronger FoxA1 and PolII binding, enhanced transcription activity, and increased FGFR2 expression level." (PMID 27825120, 2016). "Since recent studies showed that gene amplification, abnormal activation, or single nucleotide polymorphisms (SNPs) of FGFR2 played important roles in cancer progression, FGFR2 has been recognized as a promising therapeutic target for cancers." (PMID 28049184, 2016). "The residue corresponding to R669 in FGFR3 is conserved and also mutated in all other FGFRs in cancer as well as in FGFR2 in bone dysplasia." (PMID 26992226, 2016). "Differential responses (response to TKI258 and AP24534 compared with reduced sensitivity to PD173074) due to the mutation corresponding to N540K, introduced in FGFR2 in the context of the JHUEM-2 cancer cell line, have been previously observed." (PMID 26992226, 2016). "Active mutations of FGFR2 or FGFR3 are common in various cancers, whereas the oncogenic impetus of FGFR1 results mainly from either gene amplification or overexpression of wild-type receptor." (PMID 26201468, 2015). "Mapping of the FGFR2/FGFR3 cancer mutations onto the crystal structures and conformational dynamics profiles demonstrated that mutations are broadly distributed in the kinase domain occupying different segments." (PMID 24817905, 2014). "A Runx2 binding site was reported to be functional only in the minor, disease associated allele of rs2981578, resulting in increased expression of FGFR2 in cancers from patients homozygous for that allele." (PMID 24265722, 2013). "We sequenced the regions of exons (exon 3, 6, 7, 8, 9, 12, and 14) in which somatic mutations of FGFR2 have been reported in the other carcinoma cases." (PMID 23300950, 2013). "FGFR2 has been shown to be activated in a number of cancers due to gene amplification and point mutation." (PMID 22383975, 2012). "FGFR2 has been associated with a number of cancers making both of these FGFRs exciting findings for pediatric oncology." (PMID 23251904, 2012).
cancer (continued). "For some patients, this cancer is linked to a genetic change in the FGFR2 protein." (PMID 40710216, 2025). "The biological impact of FGFR2 mutations and fusions in these cancers is considerable." (PMID 39195304, 2024). "To further investigate whether the site mutations and truncated mutations of FGFR2 have cancer specificity, we studied a pan-cancer dataset of 9999 cases from a public database." (PMID 37964396, 2023). "This knowledge has the potential to guide the development of targeted therapies that specifically address the underlying molecular alterations associated with FGFR2 mutations, ultimately improving patient outcomes in EC and potentially other cancer types characterized by FGFR2 mutations." (PMID 37759450, 2023). "Furthermore, we analyzed FGFR2 site mutations and in-frame deletions in a pan-cancer approach using NGS." (PMID 37964396, 2023). "An in vitro experiment demonstrated that exon 18 truncation of FGFR2 may be a potent driver mutation that increases the response rate to FGFR inhibitors in cancer cell lines and mouse models." (PMID 37493315, 2023). "The present results indicate that pemigatinib may have anti-cancer activity in other solid tumors bearing certain FGFR point mutations other than FGFR2 fusion/rearrangement-positive CCA as approved by the regulatory in multiple regions." (PMID 37889382, 2023). "A previously poor prognostic cancer type, iCCA is now known to show distinctive molecular aberrations and targetable molecular changes; most notable are translocations of fibroblast growth factor receptor 2 (FGFR2) and, isocitrate dehydrogenase (IDH) 1/2 mutations." (PMID 35484217, 2022). "Aberration of the FGFR2 signaling pathway resulting from gene mutation, overexpression, amplification, or aberrant transcription regulation is related with the tumorigenesis and progression in cancers of the stomach, breast, bladder, and lung." (PMID 35876658, 2022). "Mutations on FGFR3 or FGFR2 genes are usually associated with the presence of cancer." (PMID 35337093, 2022). "We profiled various cancer types and provided significant and comprehensive information regarding FGFR2 abnormal expression, methylation, mutation, CNVs, and alteration that differed greatly across different cancers, which had critical therapeutic and prognostic implications." (PMID 33968743, 2021). "FGF4 promotes cancer cell proliferation, invasion and migration by causing a switch of the receptor FGFR2-IIIb, a splice variant expressed in epithelial cells, into FGFR2-IIIc, expressed in mesenchymal cells and able to induce epithelial-mesenchymal transition." (PMID 33935975, 2021). "Here, we found 309 FGFR2 somatic mutations across 32 cancer types." (PMID 33968743, 2021). "Moreover, to further explored the clinical significance of FGFR2 alteration, we analyzed survival association regarding alteration status in individual cancer types." (PMID 33968743, 2021). "However, cancer occurrences in the mutant-activated FGFR2 craniosynostoses appear confined to rare cases associated with chromosomal losses." (PMID 34007277, 2021). "FGFR2 expression in these two cancer types was associated with patient OS." (PMID 33968743, 2021). "This combination of alterations in FGFR2 will clearly impact signaling output and could be even more cancer-promoting than versions with either mutation alone." (PMID 31146385, 2019). "Maintaining the negative feedback loop ensures accurate signaling and preventing the feedback loop (either by mutation of S780 in FGFR2 or by inhibition of ERK1/2 signaling) could cause cancer progression." (PMID 31146385, 2019).
cancer (continued). "Hence in order to provide further evidence and directly assess the genetic disease risk for selfish mutations in the future offspring of cancer survivors, we have exploited our ability to quantify 12 different de novo mutations at the FGFR2 c.752–755 locus." (PMID 31348830, 2019). "At the present a huge interest is focused on FGFR2 polymorphisms, as it may have important implications in breast and other cancer carcinogeneses." (PMID 31781300, 2019). "Indeed, male germ-line-selective advantage has previously been described for mutations in other genes involved in cancer (e.g. FGFR2, FGFR3, RET, PTPN11) that cause congenital disorders with paternal age effect." (PMID 28733602, 2017). "Given the role of both FGFR2 isoforms in inducing cell proliferation, it has been observed that their altered expression can be associated to loss of proliferation control, as documented in various types of cancer." (PMID 24899248, 2014). "Since many cultured cancer cell lines are highly aneuploid, it was important to identify lines that were diploid for chromosome 10, where FGFR2 is located, in order to avoid having to target multiple FGFR2 alleles." (PMID 24265722, 2013). "Although the functionality of rs2981582 with regard to an increased cancer risk is as yet unresolved, it has been speculated that it is mediated through regulation of FGFR2 expression." (PMID 17997823, 2007). "Besides the high potency of erdafitinib against malignancies harboring FGFR2 mutations and other rearrangements, several recent studies have demonstrated its “off-target” effect to sensitize cancer cells to certain chemotherapies due to its ability to interact with ABCB1 and impair its function." (PMID 41154409, 2025). "The expression levels of FGF receptors (FGFRs), particularly FGFR1 and FGFR2, significantly differ between carcinoma and para-carcinoma tissues in colon, gastric, and esophageal cancers, implicating their role in the susceptibility and progression of these cancers." (PMID 39691707, 2024). "However, the FGFR2 isoform switch from the IIIb to IIIc isoform due to EMT is associated with cancer aggressiveness and advanced clinical stages and may limit the benefits of bemarituzumab." (PMID 39596875, 2024). "Additionally, DNA methylation was associated with FGFR2 expression in several cancers." (PMID 33968743, 2021). "Moreover, several cancer types mainly had FGFR2 mutations but relatively few amplifications and/or deep deletions, such as UCEC, SKCM, BLCA, LUSC, COADREAD, LUAD, and so on (14.9 vs. 1.7%, 9.9 vs. 0.68%, 2.43 vs. 1.46%, 2.46 vs. 1.23%, 2.69 vs. 0.34%, and 1.94 vs. 0.7%, respectively)." (PMID 33968743, 2021). "Importantly, it ignored genes that were associated with cancer in this dataset, like FGFR2." (PMID 33735170, 2021). "Furthermore, since alterations in FGFR2 expression have been linked to the pathogenesis of certain human cancers, these findings could also provide elements for diagnosis and potential targets for novel therapeutic approaches." (PMID 23613863, 2013). "In cellular models, PLW559 exhibited potent and selective antiproliferative effects against FGFR2-driven cancer cells, effectively suppressed downstream FGFR2 signalling and induced cancer cell apoptosis." (PMID 41910341, 2026). "Although fibroblast growth factor receptor 2 (FGFR2) mutations have been reported in AM, FGFR2 amplification, the predominant form of FGFR2 aberration in human cancers, remains unexplored." (PMID 42074087, 2026). "Cancer-associated fibroblasts (CAFs), for instance, secrete FGF5, which binds to FGFR2 on NPC cells and activates the Keap1–Nrf2–HO-1 axis." (PMID 40867889, 2025). "FGFR2::SHTN1 fusions were identified via cancer genomics databases and modeled using AlphaFold and HADDOCK." (PMID 41496852, 2025). "These regulatory mechanisms become particularly relevant in the context of the FGFR2::SHTN1 fusion identified in cancers." (PMID 41496852, 2025).